DNMT3A (DNA methyltransferase 3 alpha)
Diseases named in the same sentence as DNMT3A in open-access papers (continued):
Sharing a sentence is not in itself a finding about the gene and the disease.
Anxiety (20 papers, 2014 to 2025). Intense feelings of nervousness, tension, or panic often arise in response to interpersonal stresses. "Specifically, increased anxiety-like behaviors have been found to be associated with a reduction in Dnmt3a mRNA levels and global DNA hypomethylation in the adult mouse prefrontal cortex." (PMID 33668469, 2021). "CBD’s effect on the methylation status of Dnmt3a is of particular interest, since the expression of this de novo methyltransferase in the prefrontal cortex has been linked to anxiety-like behaviors in adult mice." (PMID 33668469, 2021). "Our results showing that the recovery from the anxiety-like phenotype in male BDNFV/V is associated with a reduction in Dnmt3a mRNA levels in the hippocampus are consistent with previous findings showing increased DNMT3a expression and activity in various brain regions." (PMID 38785785, 2024). "In view of the recently established studies on the role of DNMT3A in emotional behavior and anxiety, future studies may address the association between DNMT3A loss, complex neuro-psychiatric disorders and feeding behaviors." (PMID 35635747, 2022). "Paclitaxel induces DNMT3a‐dependent DNA hypomethylation in the mPFC, which contributes to paclitaxel‐induced hyperalgesia and anxiety by upregulating GABAA receptors and enhancing inhibitory transmission in mPFC glutamatergic neurons." (PMID 39679872, 2025). "Increasing the expression of Dnmt3a in the medial prefrontal cortex can reduce anxiety-like behavior." (PMID 39268349, 2024). "Our results revealed that, compared to BAY K 8644, Venlafaxine exhibited superior improvement in depression/anxiety-like behaviors and increased Dnmt3a expression." (PMID 39268349, 2024). "The recovery of the anxiety-like phenotype in male BDNFV/V mice is associated with a greater long-term decrease in HDAC1 and Dnmt3a levels and a greater increase in pCREB and Bdnf4 levels in the hippocampus." (PMID 38785785, 2024). "Previously, significantly reduced expression of DNMT3a was detected in blood samples retrieved from an anxious cohort consisting of young adults that correlated directly with anxiety severity." (PMID 35998298, 2023). "Ontological and functional analysis of genes expressed at sites of differential Dnmt3a activity would help to further elucidate its specific role in the development of the anxiety phenotype." (PMID 35998298, 2023). "Specific genes that are regulated by Dnmt3a in the mPFC, and thus, how enzyme knockdown induces the anxiety phenotype, remain elusive." (PMID 35998298, 2023). "The absence of major impairments in overall health, motor function, or anxiety-like behavior established a baseline for investigating the role of Dnmt3a in specific cognitive and social behaviors." (PMID 35604009, 2022). "Mice hemizygous for Dnmt3a also exhibit behavioral deficits, including reduced exploration and increased anxiety-like behaviors." (PMID 34685659, 2021). "On the contrary, Dnmt3a deficiency within the prefrontal cortex showed an increase of anxiety-like actions, which indicated Dnmt3a function remained controversial." (PMID 33171840, 2020). "Nonetheless, we cannot exclude the possibility of over-expressing Dnmt3a in the dDG decreases anxiety level after traumatic experience (such as fear)." (PMID 29572461, 2018). "Chronic social defeat stress was shown to induce prolonged anxiety-like behavior and to result in a reduction of DNMT3A mRNA levels and global DNA methylation levels in the medial prefrontal cortex (mPFC)." (PMID 31921466, 2017). "DNMT3A knock-down in the mPFC resulted in enhanced anxiety-like behavior similar to mice that had undergone chronic social defeat stress, while over-expression resulted in a reduction of anxiety levels." (PMID 31921466, 2017). "After being fed a diet supplemented with methyl donors ad libitum, adult mice reversed the alteration of gene expression of Dnmt3a, Dnmt3b, Grin2b and Gabar2, but anxiety-like behavior became elevated." (PMID 25144567, 2014).
Anxiety (continued). "Furthermore, it significantly increased both the number of entries into the open arms and the percentage of time spent there in the EPMT, indicating that DNMT3a overexpression effectively mitigated PTX‐induced anxiety‐like behaviors." (PMID 39679872, 2025). "Animal studies have revealed varying findings: mice experiencing depression due to social defeat exhibit lower levels of Dnmt3a expression in the medial prefrontal cortex compared to healthy controls, and up regulating Dnmt3a expression in this brain region can alleviate anxiety-like behaviors." (PMID 39268349, 2024). "This suggests that Dnmt3a in the mPFC plays a pivotal role in the development of anxiety." (PMID 35998298, 2023). "Further, exposure to chronic social stress has been observed to lead to an increase in DNA methyltransferase (DNMT) subtype 3A mRNA expression in the NAcc, and virally-mediated overexpression DNMT3A in the NAcc has been shown to promote pro-depressive and anxiety-like behaviors." (PMID 24618807, 2014). "Viral knockdown of Dnmt3a induced the same anxiety-like phenotype previously observed in CSDS mice as measured by the elevated plus maze (EPM) test, while Dnmt3a1 viral overexpression in mouse dorsal mPFC, which regulates fear, anxiety, risk taking, and decision-making, rescued CSDS-induced anxiety." (PMID 35998298, 2023). "Since our current results showed that renewal can be prevented for both recent and remote fear memory, we suggest that modulating Dnmt3a level/activity may have the potential to treat various chronic psychiatric diseases involving disregulated fear and/or anxiety." (PMID 29572461, 2018). "As a result, DNMT3a and GABAAR emerge as promising targets for managing neuropathic pain and anxiety during chemotherapy." (PMID 39679872, 2025). "Restoring DNMT3a expression in the mPFC attenuated the PTX‐induced enhancement of inhibitory synaptic transmission, alleviating both pain hypersensitivity and anxiety‐like behaviors, and conversely, inhibiting DNMT3a exacerbated these effects." (PMID 39679872, 2025). "Restoring DNMT3a levels, either through overexpression in the mPFC or a long‐term methyl donor‐rich diet, alleviated PTX‐induced pain hypersensitivity and anxiety‐like behavior." (PMID 39679872, 2025). "Overexpression of DNMT3a in the mPFC alleviates PTX‐induced pain hypersensitivity, and anxiety‐like behavior in these mice." (PMID 39679872, 2025). "Collectively, these results underscore the critical role of DNMT3a in pyramidal neurons for modulating PTX‐induced pain hypersensitivity and anxiety." (PMID 39679872, 2025). "Collectively, these findings suggest that downregulation of DNMT3a in the mPFC is crucial in the development of PTX‐mediated pain hypersensitivity and anxiety." (PMID 39679872, 2025). "While in male BDNFV/M mice the anxiety-like phenotype persisted for several days after FSS exposure, phenotype recovery in male BDNFV/V mice was accompanied by a decrease in HDAC1 and Dnmt3a and an increase in pCREB and Bdnf4." (PMID 38785785, 2024). "Mice with Dnmt3a knockout specifically in the forebrain excitatory neurons also exhibit normal PPI and anxiety-like behaviors." (PMID 34685659, 2021). "The Dnmt3a-knockout mice also had anxiety-like behavior [assessed via OFT, dark-light transfer (DLT), EPM, and home cage locomotion], whereas Dnmt3a overexpression in the medial prefrontal cortex induced an anxiolytic effect." (PMID 33101076, 2020). "Importantly, restoring DNMT3a expression in the mPFC alleviated PTX‐induced pain hypersensitivity and anxiety‐like behavior." (PMID 39679872, 2025). "Therefore, DNMT3a and GABAA receptor β1 subunit represent promising therapeutic targets for managing chemotherapy‐induced neuropathic pain and anxiety." (PMID 39679872, 2025).
Anxiety (continued). "In summary, our study uncovers a DNMT3a‐mediated epigenetic mechanism that drives the upregulation of GABAAR and hyperactivated inhibitory synaptic transmission in pyramidal neurons of the mPFC, contributing to PTX‐induced pain hypersensitivity and anxiety‐like behavior in mice." (PMID 39679872, 2025). "We subsequently examined whether DNMT3a‐dependent DNA methylation regulates the transcription of GABAAR subunit genes and whether this mechanism contributes to the pathogenesis of PTX‐induced neuropathic pain and anxiety." (PMID 39679872, 2025). "Moreover, cKO mice had no signs of increased anxiety-like behavior on three separate behavioral tests, in contrast with the reported anxiogenic effects of Dnmt3a knockdown in the mPFC of adult mice." (PMID 35604009, 2022).
pancreatic cancer (19 papers, 2009 to 2025). "We identified genetic alterations to m5C regulatory genes and patient survival outcomes in pancreatic cancer, and an association between low expression of the writer gene DNMT3A and high tumor stage." (PMID 34471186, 2021). "The age-associated decline of DNMT3A enhances IL-1α production, and disrupting IL-1R1 signaling early during tumor development normalized myelopoiesis and slowed the growth of lung, colonic, and pancreatic tumors." (PMID 39236155, 2024). "Pancreatic cancer patients with high expression of DNMT3A showed better OS compared with the low group (30.43 vs. 16.6 months)." (PMID 41465346, 2025). "DNMT3A and GMPS have also been implicated in pancreatic tumor biology, motivating a cross-tumor investigation." (PMID 41465346, 2025). "MiR-532-3p has a low expression in pancreatic cancer, but its overexpression can inhibit the tumor progression via DNMT3A-dependent inhibition of SOCS2 methylation." (PMID 37085288, 2023). "For example, the hedgehog transcription factor Gli1 targets the epigenetic modifiers DNMT1 and DNMT3a, which are positive targets of oncogenic epigenetic pathways in pancreatic cancer." (PMID 30060755, 2018). "DNMT3A is overexpressed and closely related with worse survival in pancreatic cancer." (PMID 36059626, 2022). "Moreover, immunohistochemistry result suggested the expressions of GLI1, DNMT1, and DNMT3a in pancreatic cancer tissues were higher than those in adjacent normal tissues." (PMID 24822169, 2014). "DNMT1 and DNMT3a are regulated by GLI1 in pancreatic cancer." (PMID 24822169, 2014). "In this context, the present study aims to further explore DNMT3A and GMPS as prognostic and potentially predictive biomarkers in liver cancer and pancreatic cancer, with the goal of clarifying their biological roles and translational utility." (PMID 41465346, 2025). "DNA methyl transferases (DNMTs) play a very important role in DNA methylation in cells and we observed that DNMT1, DNMT3A and DNMT3B are themselves differentially methylated in pancreatic cancer." (PMID 28423671, 2017). "Increased expression of DNMT1, DNMT3A and DNMT3B was reported in pancreatic cancer, suggesting their role in pancreatic cancer development." (PMID 27999365, 2016). "Collectively, these findings position DNMT3A and GMPS as context-dependent biomarkers that integrate metabolic and immune cues to shape prognosis in liver and pancreatic cancer, offering mechanistic insight and translational relevance for patient stratification." (PMID 41465346, 2025). "Complementary knockdown experiments using 2 specific Nupr1 siRNAs to transfect pancreatic cancer cells (MiaPaCa2) decreased Dnmt1 mRNA levels (3.8 fold ± 0.7; p < 0.01), without affecting either Dnmt3a or Dnmt3b expression." (PMID 26617245, 2015). "Notably, only DNMT3A was downregulated in pancreatic cancer, while other regulators presented no differential expression." (PMID 37332118, 2023).
non-small cell lung carcinoma (18 papers, 2014 to 2025). A group of at least three distinct histological types of lung cancer, including non-small cell squamous cell carcinoma, adenocarcinoma, and large cell carcinoma. "In this study, we conducted a case-control study to explore the association between rs1550117 A>G variant of DNMT3A gene promoter and non-small cell lung cancer (NSCLC) susceptibility in a Han Chinese population." (PMID 28423585, 2017). "UHRF1 was also shown to be overexpressed in primary non-small cell lung cancer (NSCLC) and its high expression level was associated with an increase in the expression of DNMT1, DNMT3A, and DNMT3B and correlated with hypermethylation of p16INK4A promoter." (PMID 27839516, 2016). "For example, miR-29a, which was previously reported to inhibit tumorigenicity in non-small cell lung cancer (NSCLC) by downregulating DNA methyltransferase (DNMT)3A and 3B, can suppress YY1 mRNA and protein expression levels in lung tumor cells, resulting in suppressed proliferation and migration." (PMID 37444616, 2023). "For example, Croce and his group found that levels of miRNA (miR)-29 family, including miR-29a, miR-29b, and miR-29c, were inversely correlated with the expression levels of DNMT3A and DNMT3B in non-small cell lung cancer (NSCLC) tissues." (PMID 40265378, 2025). "In non-small cell lung cancer, lncRNA TTTY15 interacts with DNMT3A and inhibits the binding of DNMT3A to TBX4 promoter, while the lower expression level of TTTY15 is associated with tumor metastasis." (PMID 35292092, 2022). "In non-small-cell lung carcinoma (NSCLC), miR-33a decreases expression of METTL3, thereby attenuating expression of target genes EGFR, TAZ and DNMT3A and suppressing NSCLC cell proliferation." (PMID 31801551, 2019). "Negative regulation of canonical Wnt signalling by miR-29 has been shown to be via targeting of DNMT3A and 3B to demethylate WIF-1 in non-small-cell lung cancer." (PMID 26687115, 2016). "We sequenced KRAS and investigated expression of NQO1 and five clinically relevant proteins (DNMT1, DNMT3a, ERK1/2, c-MET, and survivin) in 108 patients with non-small cell lung carcinoma (NSCLC)." (PMID 25222473, 2014). "The lncRNA TTTY15 could interact with DNMT3A and prevent its binding to TBX4 promoter in non-small cell lung cancer (NSCLC), the lower expression level of TTTY15 and the associated downregulation of TBX4 is connected with metastasis and worse prognosis of NSCLC patients." (PMID 36533073, 2022).
liver cancer (17 papers, 2012 to 2026). An epithelial or non-epithelial malignant neoplasm that arises from the liver. "It has been reported that miR-30b-5p is significantly downregulated in liver cancer tissues and cell lines, where it mediates DNMT3A inhibition of proliferation and targets USP37 to slow the cell cycle." (PMID 40018039, 2025). "For instance, liver cancer upregulates the expression of DNMT3a and DNMT3b, while chronic hepatitis upregulates DNMT1 and DNMT3a." (PMID 41011154, 2025). "DNMT3A was upregulated in liver cancer, and DNMT3A-mediated promoter hypermethylation inactivated multiple tumor suppressor genes, thus promoting liver cancer cell proliferation and colony formation." (PMID 36203437, 2022). "CircSOD2 acts as a sponge to adsorb miR-502-5p, represses miR-502-5p, and upregulates the expression of DNMT3a, which is target gene of miR-502-5p, thus regulating liver cancer cell progression and tumor growth in vivo." (PMID 35188072, 2022). "DNMT3A mediates miR-639 promoter methylation to accelerate tumor cell growth, migration, and invasion in liver cancer." (PMID 35860691, 2022). "In summary, these results suggest that, in liver cancer cells, DNMT3a upregulation promotes SOCS3 promoter methylation and suppresses SOCS3 expression, which further activates JAK2/STAT3 signaling pathway." (PMID 33234142, 2020). "Introducing miR-502-5p into liver cancer cells greatly suppressed DNMT3a expression, suggesting that DNMT3a is a target of miR-502-5p in HCC." (PMID 33234142, 2020). "Further analysis and experimental validation demonstrated that upregulated DNMT3a in liver cancer cells promoted SOCS3 promoter hyper-methylation and suppressed SOCS3 expression." (PMID 33234142, 2020). "In liver cancer cells, miR-30a-3p attenuates proliferation via targeting DNMT3a." (PMID 34182542, 2021). "In addition to that, we found that hampered liver cancer cell growth and cell migration induced by circSOD2 depletion were also rescued by DNMT3a." (PMID 33234142, 2020). "Similarly, in this study we also demonstrated that downregulation of DNMT3a by silencing circSOD2 impaired liver cancer cell growth and migration." (PMID 33234142, 2020). "The higher DNMT3a expression in liver cancer cells compared to normal liver cells suggests that downregulation of miR-502-5p in HCC may otherwise facilitate DNMT3a expression." (PMID 33234142, 2020). "Among emerging molecular candidates, the epigenetic writer DNMT3A and the metabolic enzyme GMPS have attracted attention for their potential prognostic significance in liver cancer." (PMID 41465346, 2025). "In the past, DNMT3a has been shown to epigenetically regulate the levels of IGFBP3 in cervical cancer by CUL4B;15 DNMT3a deprivation in liver cancer results in an increased IGFBP3 expression." (PMID 28393842, 2017).
acute lymphoblastic leukemia (16 papers, 2006 to 2024). Leukemia with an acute onset, characterized by the presence of lymphoblasts in the bone marrow and the peripheral blood. "Nonetheless, it has been observed in a mouse model that DNMT3A deletion results in an accumulation of T-cell progenitors in the thymus and lower apoptosis rates of these progenitors, with an increased risk of developing T-acute lymphoblastic leukemia (T-ALL)." (PMID 37998740, 2023). "Little is known about DNMT3A expression and its prognostic significance in childhood B cell acute lymphoblastic leukemia (B-ALL)." (PMID 36934225, 2023). "Previous studies have shown that DNMT3A is among the most frequently mutated genes in AML, MPN, MDS, and adult-early T-cell precursor acute lymphoblastic leukemia (ETP-ALL)." (PMID 32457355, 2020). "TQ has also reduced DNMT3A, DNMT3B, and DNMT1 expression in acute lymphoblastic leukemia cells (Jurkat cells)." (PMID 37375831, 2023). "TQ also has decreased the expression of DNMT1, DNMT3A, and DNMT3B in Jurkat T-cell acute lymphoblastic leukemia cells." (PMID 34959687, 2021). "Since this time, other groups have reported that Dnmt3a loss in HSPCs results in myriad types of malignancies, such as myeloproliferative disorders, AML, T-cell acute lymphoblastic leukemia (T-ALL), and B-cell acute lymphoblastic leukemia (B-ALL)." (PMID 27563627, 2016). "However, the involvement of DNMT3A in acute lymphoblastic leukemia (ALL) has rarely been reported." (PMID 23946816, 2013). "In B cells, PRDM16 and DNMT3A for AML, PDCD1LG2 for Hodgkin’s lymphoma, LMNA for spritzed tumor, and BCL11B for T-cell acute lymphoblastic leukemia (T-ALL) harbored DMPs for HIV infection." (PMID 38466776, 2024).